SRC (SRC proto-oncogene, non-receptor tyrosine kinase)
Diseases named in the same sentence as SRC in open-access papers (continued):
Sharing a sentence is not in itself a finding about the gene and the disease.
tumor (continued). "Aberrant SRC activation, frequently observed in multiple cancers, induces phosphorylation at the Y419 residue, thereby enhancing its kinase activity and promoting tumor cell proliferation, invasion, and metastasis." (PMID 41465428, 2025). "SRC inhibitors restored the reduced expression of epithelial markers, E-cadherin and Zonula Occludens-1 (ZO-1), in GC cells co-cultured with CAFs, as well as CAFs-induced aggregate formation in a 3D tumor spheroid model." (PMID 38167009, 2024). "To further confirm these findings, we established two xenograft transplantation models, and the results showed that, compared with those in the control group, the tumor volume and weight were significantly lower in the PP2 treatment group, as was the level of SRC expression in tumor tissues." (PMID 38734640, 2024). "Additionally, it acts as an anti-tumor agent by inhibiting SRC/MAPK/ERK pathways and regulating the expression of ALB, ESR1 and SRC." (PMID 39544939, 2024). "In the case of the TCGA COAD dataset, the combined ROC curve of WASL, GRB2, SRC, and Tks4 gene expression yielded the same high accuracy as before (AUC value = 0.98), indicating that the separation of normal and tumor samples is achievable based on the reduced gene set’s expression data." (PMID 39234565, 2024). "However, the combined inhibition of AKT inhibition (AKTi) + SRC inhibition (SRCi; by mk-2206 and saracatinib, respectively) can inhibit these phosphorylation activities and reactivate the tumor suppressor activity of DLC1 stabilized by EZH2i4." (PMID 39528835, 2024). "Additionally, we observed that in tumor tissues, many highly expressed MRGs are associated with CNV gains, such as MTERFD1, SRC, and MAP1LC3A." (PMID 39512680, 2024). "SRC-mediated abnormal activation of SRC kinase could promote tumor cell movement, proliferation, invasion, and metastasis." (PMID 38734640, 2024). "Additionally, an orthotopic allograft in vivo model demonstrated that the SRC inhibitor Dasatinib reduced tumor growth as a single agent, and enhanced responses to the TNBC mainstay drug, Epirubicin." (PMID 39327614, 2024). "Additionally, SRC participates in the epithelial-mesenchymal transition (EMT) process, increasing the invasive and migratory capabilities of tumor cells, which is also closely associated with chemoresistance." (PMID 39664567, 2024). "RNA analysis by qPCR with Treg cell marker genes revealed that SRC-3 KO Tregs in spleens of tumor-bearing SRC-3d/d:Treg female mice had elevated expression of anti-inflammatory cytokines such as Tgf-β, Il-10, and Il-35 compared to Tregs from the spleens of tumor-bearing SRC-3f/f female mice." (PMID 37253006, 2023). "Therapeutic strategies that target insulin/AMPK signaling and/or multi-TKI inhibitors that target ROS, ALK, KIT, FAK, TIE2, SRC, etc., may specifically target the tumor biology of these poorest-prognosis patients." (PMID 38086377, 2023). "Notably, modules containing alterations in NRAS, BRAF and SRC showed similar statistics since only four, eight and twelve mutant tumours were present in CMS4." (PMID 37666855, 2023). "Our data found that DOKD may suppress tumor development via adjusted metastasis and invasive through p-SRc/HIF-1α/Erk1/2/Snail and MMP9 signaling pathways." (PMID 37239383, 2023). "We extended the study by testing the effect of SRC overexpression on the whole tumor." (PMID 37289551, 2023). "Additionally, while we validated the feature genes and confirmed our research findings, only three genes' expressions (CSNK2A1, FUNDC1, and SRC) in tumor cells supported our results." (PMID 38155968, 2023). "The xenograft assay also showed that the decrease of SRC was indeed able to reduce tumor incidence." (PMID 36633714, 2023). "Also, our analysis of multiple tumor injections in SRC-3d/d:Treg mice showed that SRC-3 KO Tregs retained their antitumor activity for over 175 d in the mice." (PMID 37253006, 2023).
tumor (continued). "In this study, we first demonstrated that the NPC tumor suppressor THY1 could inhibit the activation of SRC." (PMID 37046850, 2023). "Our study demonstrated that THY1 could inhibit the activity of SRC, and that can resulted in the maintenance of adherens junctions and suppression of tumor metastasis in NPC for the first time." (PMID 37046850, 2023). "The signaling plasticity offered by these SRC-dependent mechanisms may usurp and/or reinforce cell-autonomous pathways that drive tumor survival while bypassing other dependencies, including under the influence of BRAF/MEK or EGFR targeted therapies." (PMID 36759733, 2023). "Estrogen can activate the SRC and PI3K/AKT pathways through binding receptors and promote the expression of nonphosphorylated β-linked proteins, thereby enhancing PC-3 cell proliferation, migration, invasion, and tumor formation." (PMID 36452480, 2022). "In summary, our study suggests that Niraparib interferes with SRC/STAT3 pathway to increase apoptosis of tumor cells with or without BRCA mutations." (PMID 36324587, 2022). "Hence, FBXL7 plays a tumor-suppressive role in preventing tumor progression, particularly metastasis, by promoting c-SRC degradation." (PMID 35906197, 2022). "Additionally, we rank ordered the pTyr sites according to their relative fold changes in each patient tumor and performed enrichment analysis of SRC substrates." (PMID 36077757, 2022). "In addition, ERα has been shown to directly interact with PI3K and SRC in a subset of invasive BC, and this complex thus represents a novel tumor biomarker to predict survival and/or response to targeted agents." (PMID 36581908, 2022). "Therefore, we suggest that ICAM-1 neutralizing antibody serves as a novel therapeutic target because it induces the inactivation of SRC and suppresses tumor malignancy." (PMID 35487888, 2022). "We also demonstrate that drug‐induced resistance to trametinib is not re‐sensitised by AZD0424 treatment in vitro, likely as a result of multiple compensatory signalling mechanisms; however, inhibition of SRC remains an effective way to block invasion of trametinib‐resistant tumour cells." (PMID 34856074, 2022). "Finally, by treating the cells with a neutralizing antibody capable of inhibiting ICAM-1, we found decreased SRC activity, tumor metastasis, and angiogenesis." (PMID 35487888, 2022). "In BC, FAK activation has been shown to be required for ErbB2-mediated oncogenic transformation, invasion and tumor progression in vivo, while SRC-mediated FAK tyrosine phosphorylation at multiple residues has been demonstrated to play an important role in full FAK activation." (PMID 36581908, 2022). "Indeed, SRC activity has been described in HNSCC and implicated in tumor progression and metastasis." (PMID 35153296, 2022). "Furthermore, we identified src42A, a Drosophila homolog of human oncogene SRC, as a direct target of Yki which is dispensable for Yki to promote tumor cell migration." (PMID 34862372, 2021). "In addition, SRC is known to promote tumor progression and glycolysis by regulating PFKFB3 activity 36-38." (PMID 33664855, 2021). "Furthermore, we identify that inhibition of the Hippo pathway promotes tumor cell migration through transcriptional activating src42A, a Drosophila homolog of the SRC oncogene." (PMID 34862372, 2021).
tumor (continued). "Although it is clear that the activity of SRC is controlled by phosphorylation, myristoylation and partner interaction, how to upregulate its expression in tumor cells still remain unknown." (PMID 34862372, 2021). "Next, we validated SRC expression as a potential biomarker in predicting response to ICT in 81 BCa patient from FUSCC cohort, and found that expression of SRC in the baseline tumour tissues correlated with improved survival benefits, but predicts worse ICT response." (PMID 33830879, 2021). "Finally, a correlation between YTHDF2 protein expression and the expressions of p-EGFR (Y1173), p-Src (Y419), and p-ERK1/2 in human gliomas also suggested the importance of this EGFR/SRC/ERK/YTHDF2 cascade in tumor development." (PMID 33420027, 2021). "Given our Drosophila data demonstrating that Yki promotes tumor cell migration through its target Src42A, we next examined whether SRC is also involved in YAP-induced HCC cell migration." (PMID 34862372, 2021). "Hypoxia may promote GBM progression and invasion throughout the integrin β3/FAK/SRC/EGFRvIII signalling axis, linking tumor cells and their surrounding environment." (PMID 32486205, 2020). "In addition, overexpression of ANO1 promotes tumor growth by activating EGFR-mediated AKT/SRC/ERK1/2 signaling or Ras-Raf-MEK-ERK1/2 signaling pathway." (PMID 32899792, 2020). "miR-654-3p acts as a tumor suppressor through regulating SRC." (PMID 33193697, 2020). "These evidences suggest that SRC targeting could be a valuable strategy to hit these pathways, and therefore impinge on tumor growth." (PMID 32545574, 2020). "Furthermore, transient overexpression of miR-205 also inhibited the expression of FAK/ERK1/2 pathway, which is crucial for tumor development, via targeting/reducing c-SRC." (PMID 32854238, 2020). "Thus, SRC activation is driven by proinflammatory cytokines, and conversely, cytokine production is driven by SRC kinases in a cross talk between tumor and inflammation." (PMID 32545574, 2020). "Notably, our results evidenced clear differences in the clinical impact of active SRC expression on patient survival depending on the tumor site." (PMID 31731442, 2019). "Importantly, we demonstrate that SRC-mediated YAP/TAZ activity promotes tumor growth and enhances metastasis and that SRC-dependent tumor progression depends, at least in part, on YAP and TAZ." (PMID 30559289, 2019). "Furthermore, cathepsin Z is essential for the activation of focal adhesion kinase (FAK) and SRC and, furthermore, cathepsins regulate tumor angiogenesis." (PMID 30669448, 2019). "First, we tested whether SRC-mediated YAP/TAZ activation is sufficient to promote tumor growth and metastasis." (PMID 30559289, 2019). "In addition, TNF-α-induced claudin-1 upregulation leads to ERK and SRC signaling activation, thus contributing to EMT and increased tumor invasion, suggesting the underlying role of claudin-1 in triggering colitis and CAC." (PMID 31316506, 2019). "Interestingly, clear differences were observed when we evaluated the impact of SRC expression on patient survival in the different tumor locations." (PMID 31731442, 2019). "LOXL2 is a member of the lysyl oxidase gene family which catalyzes the crosslinking of extracellular collagen and elastin resulting in increased ECM stiffness and subsequent activation of the kinases FAK and SRC, which enable tumor cells to proliferate and invade." (PMID 30473751, 2018). "Recurrent copy number variations are important events in SI-NET and SRC may represent a novel prognostic biomarker for this tumor type." (PMID 30219970, 2018). "Also, increased SRC-dependent PEAK1 expression by blockade of ERBB2 expression activates tumour growth." (PMID 28871116, 2017). "Using established patient-derived xenograft models that successfully retain the genomic and molecular characteristics of the parental tumor, we confirmed that these anti-tumor responses occurred through the inhibition of SRC and PI3K/AKT/mTOR signaling pathways." (PMID 27438149, 2016).
tumor (continued). "In addition, BD-138T parental tumor tissues showed significantly activated SRC and AKT, suggesting these pathways as druggable targets specific to concomitantly EGFR-amplified and PTEN-deleted MIBCs." (PMID 27438149, 2016). "Inactivation in tumor cells of adaptors that control substrate stability, such as SLAP, would also predict heightened oncogenic signaling dependent of the deregulated TK, such as SRC, and therefore may be a good predictor of tumor cell response to TKIs." (PMID 26788993, 2016). "Here, we show that the BCR-ABL/SRC inhibitor dasatinib strongly interfered with these tumour-promoting responses, suggesting that the clinical efficiency of dasatinib may be due in part to cross-inhibition of TGF-β/ALK5 signalling." (PMID 26588899, 2015). "Additionally, samples from cirrhotic patients and controls were collected at liver transplantations and tumor resections were analyzed for RhoA and c-SRC protein expression by Western Blot." (PMID 26696895, 2015). "Substrates such as p120, Hrs, Ack, p130Cas and FRK may be key mediators of SRC signaling in human tumors and contribute directly to SRC-mediated events during tumor progression." (PMID 21049007, 2010). "The identification of a critical set of SRC substrates may lead to the definition of a SRC signature that could serve as a molecular flag that SRC is active in a given tumor." (PMID 21049007, 2010). "The increased activation of SRC detected in tumor cells may therefore result from upstream activated RTKs." (PMID 21049007, 2010). "Using a PCR-RFLP assay, the occurrence of a SRC 531 mutation was ruled out in all the investigated specimens of primary tumours and/or metastases." (PMID 11161376, 2001). "Hence, SRC stood a good chance to be a crucial target of tricin-induced tumor cell suppression." (PMID 40599804, 2025). "Simultaneous inhibition of both AXL and SRC could prevent resistance and control tumor progression." (PMID 39941857, 2025). "Network pharmacology prioritized STAT3, HSP90AA1, CASP3, CASP8, and SRC as core therapeutic targets, with molecular docking confirming stable interactions between these two metabolites and targets, highlighting their potential in managing infections, neoplasms, and metabolic disorders." (PMID 41295287, 2025). "Furthermore, elevated SRC expression correlated with more advanced tumor stages." (PMID 40872629, 2025). "Key signaling molecules, including transforming growth factor beta (TGFβ) related to SRC, interleukin 1 (IL-1) associated with FOS, CXC chemokine (CXCL2), and vascular endothelial growth factor (VEGF), were highlighted due to their critical roles in tumor initiation, progression, and deterioration." (PMID 39770551, 2024). "We hypothesized that THY1 can suppress tumor invasion in NPC via inhibition of SRC." (PMID 37046850, 2023). "Notably, there was an increase in the proportion of overexpressed SRC with a higher tumor grade." (PMID 37623256, 2023). "Furthermore, the expression of SRC in these tissues was positively associated with YAP1-KLF5 module, and co-expressions of SRC and YAP1-KLF5 module were significantly correlated to the TNM stage and tumor malignancy in BCs." (PMID 36633714, 2023). "SRC inhibitors have long been recognised as potential anti‐invasive/metastatic agents to help improve progression‐free survival and metastasis‐free progression, yet most clinical trial studies incorporating SRC inhibitors monitor primary tumour growth or regression as a clinical endpoint." (PMID 34856074, 2022). "Finally, as expected, the PAIP1 and pSRC correlation results were in good agreement with data accessed via proteomic data commons for PAIP1 and phosphorylated SRC peptide (LIEDNEyTAR) at the site tyrosine 419, for paired healthy and tumor samples (P- and R-values of 0.003 and 0.724, respectively)." (PMID 35153296, 2022).
tumor (continued). "In humans, inhibiting SRC leads to a decrease in mitochondrial respiration, while higher levels of SRC were observed in various types of tumors, indicating that the SRC-mediated maintenance of mitochondrial functions may play a role in tumor cell proliferation." (PMID 33498615, 2021). "In addition to SRC, also other proteins among the non-receptor tyrosine kinase family have been associated with tumor development, including Fgr, Fyn, Yes, and Lyn." (PMID 33020459, 2020). "Thus, we can speculate that RA may influence tumor progression by targeting the expression of PTK (SYK/SRC), inhibiting the activity of RAS and attenuating the PI3K/Akt pathway and NFκB pathway." (PMID 32867345, 2020). "Here, we review how the Src-like adaptor protein (SLAP) and the suppressor of cytokine signalling (SOCS) adaptor proteins regulate the SRC and the Janus kinase (JAK) oncogenic pathways, respectively, and how their loss of function in the intestinal epithelium may influence tumour formation." (PMID 31091767, 2019). "Indeed, it is still unclear how SRC induces tumour progression in CRC." (PMID 31091767, 2019). "Next, we tested whether inhibition of SRC prevents tumor growth and metastasis." (PMID 30559289, 2019). "In addition, given the fact that inhibition of a single pathway by an inhibitor alone is almost impossible to completely suppress tumor growth in vitro and in vivo, we are currently performing experiments to identify crucial survival pathways that are up-regulated under SRC/ETS-1 inhibition." (PMID 31118072, 2019). "Interestingly, the synergism between SRC and EGFR in PCa may be associated with a more aggressive tumor phenotype." (PMID 24797896, 2014). "Together with our results showing that enhancement of the protein level of FAK, but not that of c-SRC, by barium started 5 hours after stimulation, these results suggest that another mechanism in addition to the c-SRC/FAK pathway might work in the barium-mediated tumor-promoting effects." (PMID 22022425, 2011). "RTK-induced SRC activation may also be responsible for the regulation of specific human tumor phenotypes such as cell invasion and motility, which can increase the metastatic potential of a tumor, as SRC targets substrates involved in the processes of cellular adhesion and migration." (PMID 21049007, 2010). "Single-cell sequencing showed that these targets are primarily enriched in tumor cells and macrophages, and molecular docking and dynamics simulations revealed that BBR has high affinity with SRC (-8.8 kcal/mol)." (PMID 42292805, 2026). "MMP2 and MMP9 produced by tumor cells are controlled by adipocyte-derived leptin and IL6 by activating FAK- and SRC-dependent pathways." (PMID 40841364, 2025). "TENASCIN signaling (primarily Tenascin‐C, TNC) remodels the ECM and increases matrix stiffness via integrin–FAK/SRC and mechanotransduction pathways, activates YAP/TAZ, and consequently enhances tumor cell adhesion, migration, and immune exclusion." (PMID 41498033, 2025). "Overall, the tumor cells’ autonomously enhanced glycolysis and protein lactylation modification upregulate CCL2 expression through the ENSA-K63la/SRC-pS12/STAT3-pY705 axis, thereby recruiting macrophages." (PMID 39883522, 2025). "In the TCGA LIHC and GTEx datasets, SRC and YES1 were also significantly upregulated in tumor tissues relative to normal liver tissues (p < 0.01 for both), while FGR and FYN remained unchanged." (PMID 40650282, 2025). "Nonetheless, the functions of SFKs, especially SRC and YES1, in altering the tumor microenvironment influenced by fibrosis remain largely unclear." (PMID 39776795, 2025). "These antiglioma effects of Kae have been confirmed in vivo using xenograft tumor nude mice models, demonstrating that Kae effectively inhibits tumor growth and enhances the antitumor effects of Gef by targeting the EGFR/SRC/STAT3 signaling pathway." (PMID 41009025, 2025).